CXCR4 (C-X-C motif chemokine receptor 4)
Diseases named in the same sentence as CXCR4 in open-access papers (continued):
Sharing a sentence is not in itself a finding about the gene and the disease.
limb ischemia (4 papers, 2017 to 2024). A ischemia that involves the limb. "For example, murine adipose-derived stem cells (ADSCs) that overexpress C-X-C motif chemokine receptor-4 (CXCR4) enhanced angiogenesis in a murine limb ischemia model." (PMID 39020071, 2024). "It has been reported that the elevation of CXCR4 in ADSCs enhances engraftment and homing in the limb ischemia animal model." (PMID 37263631, 2023). "CXCR4 overexpression in human adipose tissue-derived stem cells has been demonstrated to improve homing and engraftment in an animal limb ischemia model." (PMID 29057951, 2017).
metastatic melanoma (4 papers, 2013 to 2025). A melanoma that has spread from its primary site to another anatomic site. "This discovery lays a robust foundation for the development of tailored pharmacological interventions, particularly focusing on CXCR4 targeting, to address the challenges of metastatic melanoma." (PMID 38474372, 2024). "In a mouse model of metastatic melanoma, genetic deletion of one copy of CXCR4 from stromal cells significantly reduced recruitment of myeloid cells to the lung and diminished overall lung metastases." (PMID 23372646, 2013). "Among them, CDKN1A, CDKN2A, CXCR4 and RAD51 were significantly down-regulated in metastatic melanoma when compared with the primary type." (PMID 38070141, 2023).
metastatic prostate carcinoma (4 papers, 2013 to 2025). A carcinoma that arises from the prostate gland and has spread to other anatomic sites. "CXCR4 signalling is implicated in the development of metastatic prostate cancer." (PMID 39982274, 2025). "Notably, CXCR4 was shown to undergo transportin 1-dependent nuclear localization in cancerous prostate tissues and established, metastatic prostate-cancer cell lines." (PMID 25884570, 2015). "Implication of the CXCR4/CXCL12 axis in regulating the migration of human T and NK cells to BM has been reported in several studies, including in human metastatic prostate cancer." (PMID 23755121, 2013).
Miscarriage (4 papers, 2020 to 2023). A pregnancy that ends at a stage in which the fetus is incapable of surviving on its own, defined as the spontaneous loss of a fetus before the 22th week of pregnancy. "Given that CXCR4 dNK cells have great therapeutic potential in the treatment of pregnancy failures such as miscarriages, it is important to unveil the mechanisms underpinning the decrease in CXCR4+ NK cell number observed in the context of RSA." (PMID 38068544, 2023). "While Tao’s work reported the involvement of dysfunctional CXCR4+ dNK cells in the Th1 response during miscarriages, our study, in contrast, focused on the impact of trophoblast autophagy on CXCR4+ dNK cells, bridging a gap in the existing research." (PMID 38068544, 2023). "This is consistent with previous findings that CXCR4 expression in dNK cells was decreased in both miscarriage patients and abortion-prone mice." (PMID 38068544, 2023). "To better understand the role of CXCL12/CXCR4 and EEC motility in pregnancy, in the future research, we may explore their relationship with implatation failure and miscarriage, which is beneficial to find a biological target for unexplained miscarriage." (PMID 32041571, 2020).
myeloid malignancies (4 papers, 2017 to 2025). "Analysis of the glycosaminoglycan analog dociparstat sodium reveals significant activity in myeloid malignancies, mediated by specific interference with CXCL12/CXCR4 signaling cascades." (PMID 40143176, 2025). "In myeloid neoplasms like AML, significant variability exists in the CXCR4 expression as determined by PET imaging, thus limiting the suitability of this approach to a specific subgroup 25." (PMID 39744224, 2025).
non-alcoholic fatty liver disease (4 papers, 2016 to 2025). "For example, P.g can accumulate in the liver, where its fimbrial protein FimA binds to Toll-like receptor 2 (TLR2), complement receptor 3 (CR3), and CXC-chemokine receptor 4 (CXCR4), triggering various immune responses that promote the development of non-alcoholic fatty liver disease(NAFLD)." (PMID 40792109, 2025).
schistosomiasis (4 papers, 2012 to 2020). An infectious disease caused by parasitic trematodes of the genus Schistosoma that colonize human blood vessels and release eggs that can cause granulomatous reactions leading to acute (swimmer's itch or acute schistosomiasis syndrome) or chronic disease. "Treatment of schistosomiasis leads to a decrease in the level of CCR5 and CXCR4 on CD4+ cells in both HIV infected and uninfected patients." (PMID 24472559, 2014). "There were 3 chemokine receptors in cluster 2 including CCR1, CXCR4 and CXCR7, which showed sustained up-regulation during both the acute and chronic stages of schistosomiasis mice." (PMID 22905138, 2012). "However, treatment of schistosomiasis leads to a decrease in the level of CCR5 and CXCR4 on CD4+ cells in both HIV infected and uninfected patients." (PMID 24472559, 2014). "Although it is unclear whether this would be sufficient to skew the emergence of CXCR4-using C-HIV variants in our cohort, we cannot rule out the possibility that immune responses associated with schistosomiasis had some influence on the evolution of the Env phenotypes in our study." (PMID 23824043, 2013).
Sjögren’s syndrome (4 papers, 2021 to 2025). "Notably, and in contrast to previous studies of SLE ASC52, and of Sjogren’s syndrome ASC60, SLE ASC exhibit distinctive characteristics, including high levels of the chemokine receptors CXCR4 and CXCR3, largely in combination." (PMID 38429276, 2024).
synovitis (4 papers, 2018 to 2022). Inflammation of a synovial membrane. "Genes such as NRAS, SPHK2, FOS, CXCR4, PLD1, GNAI2, and PLA2G4F were strongly implicated in synovitis of OA." (PMID 29968759, 2018). "Blocking the SDF‐1/CXCR4 signaling pathway by AMD3100 administration may potentially prevent TMD patients from developing synovitis." (PMID 32449535, 2020). "As SDF-1 is strongly expressed in the synovium and bursitis, its upregulation during RA synovitis or bursitis could similarly recruit BM-MSCs in synovia or bursae through the SDF-1α/CXCR4 pathway." (PMID 31722720, 2019). "To unravel the effects of synovitis ointment on SDF-1/CXCR4, we examined the expression of SDF-1, CXCR4, MMP-9, and MMP-13 in serum under different treatment conditions through the ELISA method." (PMID 35815270, 2022). "Synovitis ointment inhibited the inflammation and bone cell fibrosis of KOA, and the mechanism was related to the SDF-1/CXCR4 singling pathway." (PMID 35815270, 2022). "Compared with the KOA group, the synovitis ointment group, the KOA + Western medicine group, and the KOA + Chinese medicine group significantly decreased the expression of SDF-1, CXCR4, MMP-9, and MMP-13." (PMID 35815270, 2022). "After applying with synovitis ointment, the expression levels of SDF-1, CXCR4, MMP-9, and MMP-13 reduced significantly in KOA rats." (PMID 35815270, 2022).
systemic sclerosis (4 papers, 2013 to 2020). A chronic disorder, possibly autoimmune, marked by excessive production of collagen which results in hardening and thickening of body tissues. "It was reported that chemokine receptors CXCR3 and CXCR4 related to lung function damage in patients with systemic sclerosis." (PMID 32582168, 2020). "The involvement of CXCR3 and CXCR4 has already been discussed in the pathogenesis of systemic sclerosis." (PMID 29566745, 2018). "The chemokine receptors CXCR3 and CXCR4 are involved in the pathogenesis of fibrosis, a key feature of systemic sclerosis (SSc)." (PMID 29566745, 2018). "Absolute numbers of circulating CD3+CD31+CXCR4+ angiogenic T cells (Tang) in healthy controls (HC) and systemic sclerosis (SSc) patients." (PMID 28797111, 2017).
T-cell acute lymphoblastic leukemia (4 papers, 2017 to 2024). Acute lymphoblastic leukemia of T-cell origin. "In a human xenograft model of T cell acute lymphoblastic leukemia, CXCR4 antagonism resulted in disease suppression, which may be related to Myc signaling downstream of CXCR4." (PMID 38786066, 2024).
abortion (3 papers, 2015 to 2023). the ending of pregnancy by removing a fetus or embryo before it can survive outside the uterus. "Diminished CXCR4+ dNK cells and their impaired ability to induce Th2 differentiation were found in RM patients and mouse models of spontaneous abortion." (PMID 34709764, 2021). "Moreover, CXCR4 expression on dNK cells was decreased in abortion‐prone mice compared to normal pregnant mice." (PMID 34709764, 2021). "Significantly upregulated CXCL12 and CXCR4 expression was detected in the uteri of IFN-γ-induced abortion mice in vivo, and CXCL12 facilitated peripheral CD49b+ NK cell migration in vitro (data not shown), suggesting an association between CXCL12 and IFN-γ-induced abortion." (PMID 26655673, 2015).
acute pancreatitis (3 papers, 2014 to 2018). An acute inflammatory process that leads to necrosis of the pancreatic parenchyma. "In 2014, Gong and colleagues reported that the SDF-1/CXCR4 axis regulated migration of MSCs toward the pancreas in a rat model of acute pancreatitis." (PMID 29879214, 2018). "In the study, we found that BMSCs can reduce severe acute pancreatitis by alleviating the systematic inflammation, promoting the formation of tubular complexes (TCs), and inducing angiogenesis involving the SDF-1α/CXCR4 axis by enhancing the expression of cell growth factors in a rat model of SAP." (PMID 25810724, 2015).
acute promyelocytic leukemia (3 papers, 2019 to 2023). An aggressive form of acute myeloid leukemia (AML), characterized by arrest of leukocyte differentiation at the promyelocyte stage, due to a specific chromosomal translocation t(15;17) in myeloid cells. "In an acute promyelocytic leukemia (APL) model (PML/RARα), green tea treatment reduced blast percentages (CD34 and/or CD117) in the bone marrow and spleen possibly through the induction of apoptosis and reduction in the CXCR4/HIF-1α signaling pathway in response to a decrease in ROS levels." (PMID 37513933, 2023).
acute respiratory distress syndrome (3 papers, 2020 to 2025). Progressive and life-threatening pulmonary distress in the absence of an underlying pulmonary condition, usually following major trauma or surgery. "We compared therapeutic properties of natural and engineered chemokine (C-X-C motif) receptor 4 (CXCR4) agonists in a rat acute respiratory distress syndrome (ARDS) model utilizing the PaO2/FiO2-ratio as a clinically relevant primary outcome criterion." (PMID 32647374, 2020). "Consistent with this dual role, mesenchymal stem cells have been shown to alleviate TNF-α- and LPS-induced apoptosis by activating the CXCL12/CXCR4 axis, thereby reducing lung injury and fibrosis in experimental acute respiratory distress syndrome (ARDS) models." (PMID 41614816, 2025). "In the complex pathophysiology of acute lung injury/acute respiratory distress syndrome (ALI/ARDS), the CXCL12/CXCR4 signaling axis exerts context-dependent effects during both injury and repair, making it a compelling yet challenging therapeutic target." (PMID 41614816, 2025).
adrenal adenomas (3 papers, 2022 to 2025). "CXCR4, a G-protein-coupled chemokine receptor expressed on the surface of the cell membrane, was reported to be upregulated in adrenal adenoma." (PMID 36010286, 2022). "However, notably, individual studies have reported increased uptake of CXCR4-targeted 68 Ga-PentixaFor in cortisol-producing adrenal adenomas." (PMID 39375255, 2025). "Recently, PET/CT with 68Ga-pentixafor, a CXCR4-specific PET tracer, was reported to exhibit great potential for identifying functional adrenocortical adenomas." (PMID 36010286, 2022). "Imaging agents for these targets (CXCR-4 and CYP11B2) have the advantage of identifying adrenal adenomas based on the expression/overexpression of targets not generally seen in normal adrenal tissue, and likely have clinical utility for primary aldosteronism detection." (PMID 35483964, 2022).
alopecia areata (3 papers, 2024 to 2026). Loss of scalp and body hair involving microscopically inflammatory patchy areas. "It has been demonstrated that CXCL12 inhibits hair growth via CXCR4, and its neutralizing antibody (Ab) increases hair growth in alopecia areata (AA)." (PMID 39483478, 2024).
astroglioma (3 papers, 2015 to 2023). "SDF-1 and CXCR4 were the most frequently expressed mRNA identified in 31 human astrocytic neoplasms." (PMID 37790751, 2023). "Among various chemokine receptors and their ligands tested, mRNA expression of both CXCL12 and CXCR4 were identified in the highest percentage of human astrocytic tumor samples." (PMID 32456359, 2020). "IL-1β has been reported to up-regulate CXCR4 expression in astroglioma cells." (PMID 26176534, 2015).
central nervous system lymphoma (3 papers, 2010 to 2024). "Gene alterations in BTG2, PIM1, DUSP2, ETV6 and CXCR4 had been identified in more than 20% of patients with primary CNS lymphoma (PCNSL) in a study by Wang and colleagues." (PMID 38173015, 2024).
cervical adenocarcinoma (3 papers, 2010 to 2021). An adenocarcinoma arising from the cervical epithelium. "An additional study showed that CXCR4 expression is associated with pelvic lymph node metastasis in cervical adenocarcinoma and the addition of CXCL12 provoked significant signal transduction events, including chemotaxis and rescue from apoptosis." (PMID 34833360, 2021). "This increased CXCR4 expression has also been demonstrated in patients with squamous cell and adenocarcinoma of the cervix who had a large tumor size, deep stromal invasion, involvement of the lymphatic space, or lymph node metastasis." (PMID 34833360, 2021).
chronic allograft nephropathy (3 papers, 2013 to 2024). "CXCR4 is a clinically useful parameter for the identification of subjects with a high risk of acute rejection, chronic allograft nephropathy, and graft failure." (PMID 24386129, 2013). "Furthermore, CXCR4 induces epithelial-mesenchymal transition (EMT) through activation of the Wnt/β-catenin signaling pathway in rat chronic allograft nephropathy, consistent with another report suggesting CXCR4 involvement in the JAK/STAT/GSK3β/β-catenin pathway activation in the UUO model." (PMID 39684834, 2024). "CXCR4 plays a critical role not only in the process of homing but also in the pathogenesis of acute rejection and chronic allograft nephropathy, in which both immune- and non-immune-mediated mechanisms are involved." (PMID 24386129, 2013).
chronic obstructive pulmonary disease (3 papers, 2009 to 2023). A chronic and progressive lung disorder characterized by the loss of elasticity of the bronchial tree and the air sacs, destruction of the air sacs wall, thickening of the bronchial wall, and mucous accumulation in the bronchial tree. "For example, DNA methylation of the CXCR4 gene was associated with inflammation in chronic obstructive pulmonary disease (COPD) patients." (PMID 37445852, 2023).
cognitive decline (3 papers, 2021 to 2025). "C‐X‐C chemokine receptor type 4 (CXCR4) synergizes with the chemokine CXCL12 to mediate inflammatory responses and cognitive decline in patients with AD." (PMID 37334737, 2023).
congenital heart disease (3 papers, 2019 to 2024). A heart disease that is present at birth. "Increased expression of CXCR4, a receptor for the chemokine stromal cell-derived factor 1 (SDF1), was reported in the lungs of patients with IPAH, HPAH, and PAH associated with congenital heart defect." (PMID 31979420, 2020). "WHIM patients display an increased incidence of non-hematopoietic conditions, such as congenital heart disease suggesting that abnormal CXCR4 may put these patients at increased risk of congenital anomalies." (PMID 30819232, 2019).
dilated cardiomyopathy (3 papers, 2016 to 2022). Cardiomyopathy which is characterized by dilation and contractile dysfunction of the left and right ventricles. "In mice with dilated cardiomyopathy, pharmacologic antagonism of stromal cell-derived factor-1/CXCR4 signaling with AMD3100 was shown to decrease splenic CD4 + T cell abundance and cardiac fibrosis and improve diastolic and systolic myocardial performance." (PMID 35048778, 2022). "In mice with experimental dilated cardiomyopathy we showed that administration of AMD3100, a highly selective CXCR4 antagonist, was associated with a marked reduction in perivascular and interstitial fibrosis, supported by a reduction in the expression of collagen I mRNA." (PMID 30837882, 2019). "In the present study we addressed the hypothesis that selective CXCR4 antagonism might prevent the development of myocardial fibrosis in an experimental model of dilated cardiomyopathy." (PMID 30837882, 2019). "The primary objective of the study was to investigate the effect of the CXCR4 antagonist, AMD3100, on ventricular structure and function in mice with dilated cardiomyopathy." (PMID 30837882, 2019). "Methods and Results: We studied the effect of a highly selective antagonist of SDF-1/CXCR4 signaling, AMD3100, on the development of cardiac fibrosis and cardiac function in mice with dilated cardiomyopathy due to cardiac-specific transgenic overexpression of the stress-kinase, Mst1." (PMID 30837882, 2019). "Taken together, the present study shows, for the first time, that chronic CXCR4 antagonism can exert an anti-fibrotic action which is accompanied by evidence of improved cardiac performance in non-ischemic, dilated cardiomyopathy." (PMID 30837882, 2019).
dyslipidemia (3 papers, 2021 to 2024). "Although different associations with cardiometabolic risk factors indicate disease-specific changes, overlapping pattern was found for the associations between CCR4+ T lymphocytes and vascular inflammation, CXCR4+ subsets and albuminuria as well as CXCR3+ T lymphocytes and dyslipidemia." (PMID 39109081, 2024).
endometrioid carcinoma (3 papers, 2017 to 2023). "More recently, it has been showed that CD133+ cells purified from endometrioid adenocarcinomas are resistant to cisplatin-induced and paclitaxel-induced cytotoxicity and express a peculiar gene signature consisting of high levels of matrix metalloproteases, interleukin-8, CD44, and CXCR4." (PMID 28531111, 2017).
epilepsy (3 papers, 2019 to 2025). A brain disorder characterized by episodes of abnormally increased neuronal discharge resulting in transient episodes of sensory or motor neurological dysfunction, or psychic dysfunction. "Our findings demonstrate that maternal anesthesia impairs interneuron migration through the CXCL12/CXCR4 signaling pathway, and influences the interneuron properties, leading to the increased epilepsy susceptibility in adolescent offspring." (PMID 38129829, 2023). "Furthermore, the CXCL12/CXCR4 signaling pathway played an important role in the migration defects of interneurons which may contribute to the increased epilepsy susceptibility in adolescent offspring." (PMID 38129829, 2023). "Previous studies have reported a role for the CXCL12/CXCR4 pathway in regulating spontaneous epileptiform discharges in epilepsy via modulation of adult neurogenesis of hippocampal dentate GCs9,10." (PMID 31672961, 2019). "Due to the close relationship among CXCL12, CXCR4, and CXCR714, we predicted that CXCR7 plays a role in regulating hippocampal adult neurogenesis in epilepsy." (PMID 31672961, 2019). "However, the expression patterns of CXCL12, CXCL11, CXCR4, and CXCR7 in epilepsy remain unclear." (PMID 31672961, 2019). "We found no significant changes in CXCR4, CXCL11, and CXCL12 expression levels in the hippocampus of mice with KA-induced epilepsy or in the brain tissues of patients with TLE." (PMID 31672961, 2019).